CXCL10 (C-X-C motif chemokine ligand 10)
Diseases named in the same sentence as CXCL10 in open-access papers (continued):
Sharing a sentence is not in itself a finding about the gene and the disease.
tumor (continued). "In monocytes, a significant increase in CXCL10 production was observed in the one-shot and five-shots groups, compared to that under tumor transplantation." (PMID 38002062, 2023). "In our current study, we further demonstrated that the chemokine CXCL10 was involved in the synergistic anti-tumor effect induced by the combination therapy of MWA and anti-PD-1." (PMID 36900218, 2023). "CXCL10 regulates several hallmarks of the tumor microenvironment and especially modulates the infiltration of anti-tumoral T cells." (PMID 36982370, 2023). "The macroC5 cluster, characterised by the overexpression of proinflammatory factors such as CXCL10, would have a significant impact on drawing T cells, NK cells and DCs to the tumour microenvironment." (PMID 37784253, 2023). "STING also increases the expression of chemokines, such as CXCL9 and CXCL10, which attract T lymphocytes to tumor tissue, promote tumor cell killing, and initiate adaptive immune responses." (PMID 37719852, 2023). "Several chemokine ligands are expressed by the tumor: CCL17 and CCL22 promote recruitment of CCR4+ Tregs, while CXCR3—along with its ligands, CXCL9 and CXCL10—drives cytotoxic lymphocyte trafficking into the GBM tumor site." (PMID 37443804, 2023). "There are reports on the correlation between the prognosis of tumor patients and the level of CXCL10." (PMID 37048082, 2023). "Several studies have shown that activation and infiltration of CD8+ cytotoxic T cells and NK cells are reliant on type I interferon (IFN) such as IFNβ, and chemokines such as CCL5 and CXCL10 in the tumor microenvironment." (PMID 37079538, 2023). "ELISA measurements in B7H4 staining positive tumours: IL-9, IL-18, IP-10(CXCL10), MIG (CXCL9) and SDF-1a (CXCL12)." (PMID 36980202, 2023). "While, the in vivo experiments showed the tumor-associated macrophages (TAMs, F4/80+ CD11b+ CD45+ L/D-) and DCs (CD11c+ CD45+ L/D-) cells sorted from TIICs had significantly higher CXCL10 expression in the LDRT group than those in the CON group." (PMID 38001101, 2023). "Prior to conducting the assay, we identified a subset panel of factors known to mediate the induction of apoptosis in tumor cells: IL-27, IL-1b, IL-2, CXCL10, IL-12p70, G-CSF, IFN-g, TNF-a, IFN-a, CCL2, IL-9, TNF-b, TRAIL, IL-18, IL-21, TSLP." (PMID 37468934, 2023). "Resultant expression of soluble mediators such as CCL5 and CXCL10 can facilitate recruitment of dendritic cells and immune effector cells into the tumor." (PMID 37079538, 2023). "We propose that CXCR3highCD8+ T in healthy volunteers exhibited anti-tumor capacity by CXCL10/CXCR3-activated LFA-1-ICAM-1 interaction and resulted in consequent CD8+ T cell activation." (PMID 36688994, 2023). "Further, CXCL9 was positively related to CCL4, CCL5, CXCL10, and CXCL11 in UCEC, which are associated with DC, NK, and T cell recruitment and play an essential role in suppressing tumor growth and improving prognosis." (PMID 36845675, 2023). "Type I and II IFNs are known to induce the production of cytokines, including CXCL9 and CXCL10, which play a role in immune cell migration, differentiation, and activation and ultimately in tumor suppression." (PMID 37478172, 2023). "Overall, these data supported that the stem-like CD8+ Tpex enhanced by LDRT were mainly recruited from the dLNs into the tumor through the CXCL10/CXCR3 axis." (PMID 38001101, 2023). "Another study revealed that IRF1 increased CD8+ T cells, NK and NKT cells migration, and activated IFN-γ secretion in NK and NKT cells to induce tumor apoptosis through the CXCL10/CXCR3 paracrine axis in HCC." (PMID 37051536, 2023). "In the paired analysis of local hospital database, the expression level of CXCL10 in the tumor samples was significantly higher than that in the normal samples." (PMID 36782176, 2023).
tumor (continued). "The STING-induced production of chemokines such as CXCL9, CXCL10 and CCL5 promote further recruitment of immune cells into the TME, and high levels of STING expression in tumours has been linked to overall higher immune cell infiltration in cancers." (PMID 37534795, 2023). "The anti-tumor neutrophils induced via BCG exhibited upregulated CXCL10 and MHC class II expression levels." (PMID 38002062, 2023). "We investigated associations of a 4-chemokine expression signature (c-Score: CCL4, CCL5, CXCL9, CXCL10) with metrics of antitumor immunity across tumor types." (PMID 37558751, 2023). "In parallel, “find me” signals, such as C-X-C motif chemokine ligand 10 (CXCL10), are released from immunogenically dying tumor cells, promoting intratumoral infiltration of anti-tumor T-cells." (PMID 37553327, 2023). "In contrast, some reports have indicated a high correlation between CXCL10 production and poor tumor prognosis." (PMID 37048082, 2023). "Our results indicate that epigenetic priming mediates the rapid secretion of key tumor-derived cytokines known to augment T and NK cell activation and cytotoxicity, including IL-6, IP-10 (CXCL10), KC (CXCL1), and RANTES (CCL5)." (PMID 37627156, 2023). "IHC staining for DPP4 expression in tumor tissues showed that DPP4 was expressed in the stromal tissues of all nude mice implanted with tumor cells, suggesting that only CXCL10 produced by the implanted cells was inactivated by DPP4." (PMID 37218983, 2023). "Decitabine (DAC), an inhibitor of DNA methylation transferase, is able to induce CXCL10 expression in tumor cells and suppress anti-tumor T-cell responses and hepatoma proliferation when administered to HCC mice." (PMID 37020540, 2023). "A recent report revealed that treatment of hepatocellular carcinoma cells with EZH2i GSK126/343 was able to increase CXCL10 expression by tumor cells, which induced NK cell migration to the tumor site and suppressed tumor growth in a mouse model." (PMID 37090711, 2023). "The other showed that the combination of MEK inhibitors and chemotherapy promoted the secretion of CXCL10 by cancer cells and the recruitment of tumor-specific cytotoxic T cells." (PMID 37187618, 2023). "Such DAMPs also promote type I IFN secretion, and further trigger CXCL10 secretion that promotes the recruitment of immune effectors to the tumor." (PMID 37190135, 2023). "Pancreatic tumor cells can also express Cxcr3, and Cxcr3:Cxcl10 interactions facilitate tumor cell migration to sensory neurons and contribute to cancer-related pain." (PMID 36472588, 2023). "The inhibitory effects of IL-12 on tumour vasculature were also associated with increased levels of the IFN-γ-inducible chemokine ligands CXCL9 and CXCL10 (IP-10) and decreased production of vascular endothelial growth factor (VEGF)." (PMID 37629081, 2023). "CXCL10 elicits strong inflammatory effects and is also known to recruit the tumor antigen-specific CD8+ T cells into tumors; however, its stability and downstream functions in the tumor environment are not clear." (PMID 37445941, 2023). "Three of these cytokines (IP-10/CXCL10, IL-6, and PDGF-AA) were also among those consistently associated with the tumor dimensions in all—current and previous—vitreous studies of UM." (PMID 37509362, 2023). "Six out of 18 chemokines/cytokines assessed were significantly decreased in the ascites from NLRC5+ tumor-bearing mice, including IL-6, IL-10, IL-12, CXCL10, CCL5, and to a greater extent, CCL2." (PMID 38235131, 2023). "In the present study, we investigated the role of CXCL10 in thermal-ablation-based tumor immunotherapy by analyzing scRNA-seq data of CD45+ immune cells in tumors from the non-thermal-ablation side of Panc02 tumor-bearing mice from a published database." (PMID 36900218, 2023). "Inhibition of nSMase2 decreased the expression of VCAM1, CX3CL1, and CXCL10 by ECs and reduced T cell tumor infiltration." (PMID 36901858, 2023).
tumor (continued). "CXCL10 was also proved to regulate tumor immune microenvironment of ovarian cancer, leading to strong immune cell infiltration." (PMID 37393391, 2023). "In melanoma studies, it has been observed that activation of STING in tumor cells and DCs leads to increased infiltration of NK cells in the tumor microenvironment (TME) through the secretion of CXCL10 and CCL5 cytokines." (PMID 37781382, 2023). "TAMs in HCC can secrete various cytokines and chemokines, such as IL-1β, IL-6, TNF, CCL2, and CXCL10, promoting tumour cell proliferation and NF-κB-mediated protection against cancer cell apoptosis, which is associated with a poor prognosis in HCC patients." (PMID 37542324, 2023). "This seems to be guided by chemokines such as CXCL12, CXCL10 and CCL2, produced by various cell types such as tumor cells, and tumor-associated macrophages and fibroblasts." (PMID 36766797, 2023). "Nevertheless, LAC injection in tumor effectively liberated IL-12 and IFN-γ and thus elevating downstream chemokines CXCL-9 and CXCL-10, particularly in RNF8 deficient mice." (PMID 37391451, 2023). "In our present study, we found that the reduction in tumor progression by anti-PD-1 treatment in MC38 tumor models was dependent on CXCL10." (PMID 36900218, 2023). "The frequency of tumor cells expressing apical Cxcl9/Cxcl10 was significantly decreased in KPC recipients of 1045 T cells or 1045 T cells + CD40 agonist." (PMID 36472588, 2023). "Surprisingly, CXCL10 also promoted tumor cell migration in mouse models, and CXCL10 secreted by mesenchymal stem cells promoted tumor growth." (PMID 38075694, 2023). "Deletion of the IL30 gene in PC cells inhibits endothelial expression of IGF1, EDN1, ANG and CXCL10 and substantially impairs tumor angiogenesis." (PMID 38087324, 2023). "Cell–cell interaction analysis within tumor tissues also confirmed that TeMs participated actively in the recruitment of T cells through CXCL10/11–CXCR3, CCL3/4/5–CCR5 and CXCL12–CXCR4 signaling." (PMID 37488416, 2023). "Particularly interesting to tumor cellular organization, CXCL10 was enriched within 2HC T cells, known to be a T cell recruitment factor." (PMID 38085642, 2023). "GSK126 played a vital role in promoting IFN-γ, which increased CXCL9 and CXCL10 expression in the tumor, promoting T cell proliferation, maturation, activation, and chemotaxis into GBM, thereby inhibiting tumor growth and prolonging survival." (PMID 38104126, 2023). "Surprisingly, expression of IL-12, IFN-γ, CXCL-9, and CXCL-10 in tumor center was dramatically decreased than tumor periphery." (PMID 37391451, 2023). "The cDC1s also secrete different chemokines (CXCL9, CXCL10) required to attract cytotoxic lymphocytes into the tumor microenvironment, essential for the response to CAR T-cell therapy." (PMID 37190135, 2023). "Cisplatin induces an increase in CCL20 and IL-1β in tumor cells within a cold tumor model, both of which activate ILC3s to release the chemokine CXCL10, attracting CD4 T and CD8 T lymphocytes to infiltrate tumor tissue and then exert anti-tumor effects." (PMID 37122757, 2023). "We further find that epigenetic priming induces increased tumor secretion of several key cytokines known to augment T and NK cell activation and cytotoxicity, including IL-6, IP-10 (CXCL10), KC (CXCL1), and RANTES (CCL5)." (PMID 37627156, 2023). "Unexpectedly, Cxcl9/Cxcl10 was largely confined to the apical surface in tumor cells from untreated KPC mice." (PMID 36472588, 2023). "In contrast, in Cxcl10−/− mice, the inhibition of tumor growth by MWA was diminished and the overall survival rate was much lower than that of wild-type mice." (PMID 36900218, 2023). "According to TCGA database, we found that CXCL10 expression was generally elevated in tumor tissue (n = 162) than that in normal tissue (n = 11) samples (P < 0.001)." (PMID 37903782, 2023).
tumor (continued). "Blocking ATX activity changed the phenotype of the mice by decreasing the plasma concentrations of CXCL9, CXCL10, and CCl2 and the tumor concentrations of LIF, TGFβ1, TGFβ2, and prolactin." (PMID 37296899, 2023). "Next, we inoculated MC38 tumor cells bilaterally on the back of C57BL/6 and Cxcl10−/− mice and treated one side of the tumor with MWA." (PMID 36900218, 2023). "Recent study indicated that under-expression of CXCL10 was related with tumor metastasis and poorer OS." (PMID 37198617, 2023). "When AT-3 tumors were injected into CXCL9/CXCL10 double-knockout hosts or hosts depleted of macrophages, the anti-tumor response of the checkpoint blockade was completely lost." (PMID 38140561, 2023). "Mechanistically, LDRT sensitized DPVB by enlarging intratumoral stem-like CD8+ Tpex, which were recruited from the draining lymph nodes (dLNs) into the tumor through the CXCL10/CXCR3 axis." (PMID 38001101, 2023). "It was shown that ex vivo expansion of NK cells in the coculture of IL-2 and feeder cells (EBV-LCLs) significantly upregulated the expression of CXCR3 on NK cells, resulting in increased migratory capacity toward CXCL10-producing tumor cells in vitro." (PMID 38264648, 2023). "CXCL10 is a cytokine believed to promote immunosuppression and tumor stemness while CXCL16 has a beneficial effect on cancer control since it promotes lymphocyte infiltration in the tumor." (PMID 37006319, 2023). "Measurement of tumor volume and body weight revealed that IDO1 overexpression drove tumor growth, whereas CXCL10 knockdown showed an inhibitory effect (P < 0.01)." (PMID 37903782, 2023). "Intratumorally administered Alu-NPs elicited significantly increased gene expression of Ifnb1, Cxcl10, and Tnf in the tumor microenvironment (TME)." (PMID 37691856, 2023). "Chemokines are secreted proteins structurally similar to cytokines and play an important role in regulating the migration of immune cells and the proliferation of tumor cells, including CXCL10, which possess a strong pro-inflammation capacity." (PMID 37187618, 2023). "In the context of HL, CXCL10 expression has been detected in Reed–Sternberg cells and in cells within the tumor microenvironment." (PMID 37958472, 2023). "In another study, the expression of IFNγ-induced chemokine CXCL10 in the tumor negatively correlated with tumor size and microvessel density (MVD) but positively correlated with the number of infiltrating CD8+ cells." (PMID 37445941, 2023). "Protein levels of CXCL9 and CXCL10 were markedly higher in tumor-bearing brains after T-αFGL2 treatment compared to T-Ctr treatment." (PMID 36759517, 2023). "This demonstrated significantly higher expression of CXCL9 and CXCL10 for the anti-tumor immune-suppressive M2 tumor-related macrophage family than for the M1 macrophage (p = 6 × 10−27, 8 × 10−6, respectively)." (PMID 37686653, 2023). "More specifically, CD274 expression was highest in Macro CXCL10 and Macro CXCL10 derived from responding tumours displayed higher CD274 expression (Fig. 5cbottom)." (PMID 38030622, 2023). "Activated ILC3s produce the chemokine CXCL10 which mediates the recruitment of T cells to the tumor, promoting anti-tumor immunity and increasing the efficacy of ICB treatments." (PMID 37514187, 2023). "The induction of chemokines such as CXCL-9 or CXCL-10 by IFN-λ recruits CD4+ T cells into the tumor environment, and antitumor responses of CD8+ T cells and natural killer (NK) cells are enhanced in various types of tumors." (PMID 37374093, 2023). "Targeting this axis directly with monotherapies to block the CXCL9/CXCL10/CXCL11–CXCR3 axis or to regulate CXCR3-A expression on the tumor cell membrane surface holds promise." (PMID 38104126, 2023). "Single-cell analysis and vitro experiments further confirmed the potential secretion of CXCL10 by macrophages and its involvement in lymphangiogenesis within the tumor microenvironment." (PMID 37273921, 2023).
tumor (continued). "A recent study showed that CXCL9 and CXCL10 from macrophages are critical for the recruitment of T cells in the tumor microenvironment." (PMID 36978108, 2023). "Conditioned tumor cell medium treated with 10 μM 5-aza showed upregulation of 4 key cytokines—IL-6, IP-10 (CXCL10), KC (CXCL1), and RANTES (CCL5)—which activate both adaptive and innate immune responses." (PMID 37627156, 2023). "A separate preclinical NSCLC study determined that anti-CD40 immunotherapy response was dependent on a subset of anti-tumor TANs with an interferon gene signature and elevated CXCL10 secretion." (PMID 37830618, 2023). "Specifically, interferon-gamma (IFN-γ) and its induced production of CXCL9 and CXCL10 contribute to the establishment of an inflammatory tumor microenvironment, which plays a role in the tumor’s response to ICIs therapy." (PMID 37835371, 2023). "A similar study employed a tumor-homing immune nanoregular (THINR) for the local release of CXCL10 in residual GBM tumors to exert tumoricidal effects." (PMID 38104126, 2023). "We found that the MWA plus anti-PD-1 treatment had a better synergistic anti-tumor effect in MC38-bearing wild-type mice compared with Cxcl10−/− mice." (PMID 36900218, 2023). "As a chemokine, CXCL10 promoted the recruitment of NK cells to tumor sites, exerting a tumor-suppressive effect through NK-cell-mediated tumor cell growth inhibition without affecting the killing activity of NK cells on hepatoma cells." (PMID 37268997, 2023). "This correlated with an upregulation of the chemokines CCL5, CCL19, CXCL9, and CXCL10 expression from the tumor." (PMID 38022679, 2023). "Based on these results, it is possible that the induction of CXCL10 promoted the infiltration of CD8+ T cells into the tumor and resulted in good therapeutic efficacy." (PMID 38133557, 2023). "This study also demonstrates that high CXCL10/STAT2 expression (HH subgroup) is associated with activation of T-cell pathways, increased tumor infiltration of Th1 and CD8+ T cells, and good patient prognosis." (PMID 35207629, 2022). "In response to Alb-IFNβ, we observed an upregulation in CXCL9 and CXCL10 expressions in the tdLNs, which are chemoattractants secreted by DCs to recruit T cells to the tumor." (PMID 35459734, 2022). "In view of their ability to promote effector T cell differentiation, CXCL9 (and CXCL10) are investigated as effector molecules for enhancing anti-tumor immunity and restraining tumor growth." (PMID 35967369, 2022). "Altogether, these data suggest that CXCL10 shapes the TME affecting tumor cell proliferation, angiogenesis and death of infiltrating stromal immune cells." (PMID 35897689, 2022). "IL-1β, IL-6, CXCL8, CXCL10, and vascular endothelial growth factor comprise the M2 TAMs that contribute to cancer metastasis, immune suppression, and tumor growth." (PMID 36239108, 2022). "Mast cells are recruited by the microenvironmental chemokines, such as CCL2, CXCL1, CXCL8/IL8, and CXCL10, to tumor tissues, and are activated by pro-inflammatory cytokines, such as stem cell facto (SCF), IL33, PGE2, leukotriene B4, and osteopontin, in there." (PMID 36211375, 2022). "Elevated levels of G-CSF, IL-6 and CXCL13, and B cell counts were associated with 4T1 growth, whereas CCL17, CXCL10, total myeloid cells, CCL2, IL-10, CXCL1, and Ly6Cintermediate monocytes were associated with CT26 tumour development." (PMID 35226704, 2022). "Tumor-specific type 1 CD8+ T cells (mainly secreting IFN-γ) can effectively enter brain tumor sites through the type 1 chemokine CXCL10 and effectively kill tumor cells." (PMID 35769466, 2022).